STK32C (serine/threonine kinase 32C)
Synonyms: YANK3; PKE; MGC23665
Tractability: Small molecule: a high-quality ligand is known; it belongs to a druggable protein family. PROTAC: it is named in the literature on targeted protein degradation; ubiquitination databases record sites on it; its protein half-life has been measured; a small molecule that binds it is known.
Target class: Kinase; AGC protein kinase YANK family; Enzyme; Protein Kinase; AGC protein kinase group
Gene: Protein-coding gene on chromosome 10 (132,207,483 to 132,331,847, reverse strand). Ensembl gene ENSG00000165752.
Gene Ontology:
Molecular function: protein binding; protein serine kinase activity; protein serine/threonine kinase activity; ATP binding; protein kinase activity
Biological process: intracellular signal transduction
Genetic constraint (gnomAD): Loss-of-function variants: 31 observed, 48.46 expected, observed/expected ratio (o/e) 0.64, 90% interval 0.48 to 0.86. The upper end of that interval is the gene's LOEUF score, 0.86, which puts it in group 3 of 6, group 1 being the genes least tolerant of losing a copy. Missense variants: 504 observed, 551.84 expected, observed/expected ratio (o/e) 0.91, 90% interval 0.85 to 0.98. Synonymous variants: 282 observed, 233.91 expected, observed/expected ratio (o/e) 1.21, 90% interval 1.09 to 1.33.
Homologues: Orthologues: chimpanzee STK32C (99% identical), macaque STK32C (97% identical), rat Stk32c (92% identical), mouse Stk32c (91% identical), pig STK32C (91% identical), dog STK32C (89% identical), guinea pig STK32C (83% identical), tropical clawed frog stk32c (70% identical), Drosophila melanogaster CG32944 (43% identical), Caenorhabditis elegans M03C11.1 (34% identical), Drosophila melanogaster dop (29% identical), Caenorhabditis elegans kin-4 (27% identical), and 2 more. Paralogues in human: STK32B (55% identical), STK32A (52% identical), MAST2 (32% identical), MAST3 (31% identical), MAST4 (31% identical), MAST1 (29% identical), LATS1 (25% identical), LATS2 (25% identical), SGK1 (24% identical), SGK3 (24% identical), SGK2 (22% identical), DMPK (20% identical), and 1 more.
Diseases named in the same sentence as STK32C in open-access papers:
STK32C is named in the same sentence as 16 diseases in open-access papers, as found by Europe PMC text mining. Sharing a sentence is not in itself a finding about the gene and the disease. The quoted sentences say what the papers report.
depression (5 papers, 2014 to 2025). "Two DMPs associated with ECTresp were annotated to STK32C, a protein kinase which was shown to display differences in methylation in monozygotic twins discordant for depression." (PMID 41339323, 2025). "The second small trans-acting hotspots involved a SNP upstream from the gene STK32C which is highly expressed in the brain and has been linked to, for example, Alzheimer's disease and depression." (PMID 37039566, 2023). "Further studies displayed that the top differentially methylated probes were located within STK32C and hypomethylation of a CpG site in an intron of STK32C in individuals may contribute to depression disorder." (PMID 36353114, 2022). "Two reproducible depression-associated DMPs were identified, including the top-ranked DMP that was located within STK32C, which encodes a serine/threonine kinase, of unknown function." (PMID 24929637, 2014). "Other studies that investigated DNA methylation signatures of depression in discordant monozygotic twins study design implicated epigenetic changes in VDR26, HOXB7, CACNA1C, STK32C, NR1C3, and MYC genes among others, but not in KLK8 or DAZAP247,108,117,118." (PMID 31477683, 2019).
bladder cancer (3 papers, 2022 to 2025). "Emerging evidence implicates serine/threonine kinase 32C (STK32C) overexpressed in bladder cancer and brain tissues acts as a molecular target for doxorubicin resistance, yet its role in colorectal cancer (CRC) remains unclear." (PMID 41208890, 2025). "It has been shown that inhibition of LAPTM5 blocks bladder cancer cell proliferation and cell cycle via deactivation of ERK1/2 and p38 and that silencing of STK32C inhibited tumor cell proliferation, migration, and invasion in human bladder cancer cells." (PMID 36139698, 2022).
breast carcinoma (2 papers, 2025). "Bioinformatics analysis was conducted with TCGA dataset to identify STK32C expression level in colon, bladder and breast cancers and normal tissues." (PMID 41208890, 2025).
colorectal cancer (1 paper, 2025). A primary or metastatic malignant neoplasm that affects the colon or rectum. "Publicly available datasets showed variable endogenous expression of STK32C among colorectal cancer cell lines (n = 63)." (PMID 41208890, 2025). "We also investigate whether inhibition of STK32C can potentiate the antitumor effects of 5-FU, thereby positioning STK32C as a molecular target to enhance chemotherapy in colorectal cancer." (PMID 41208890, 2025). "In summary, in our current study, STK32C was overexpressed in HCT116, HT29, SW480, and SW620 colorectal cancer cells compared to CCD-18Co normal fibroblast cells, and its overexpression was associated with poor OS and DFS rates." (PMID 41208890, 2025). "Regarding the interaction between STK32C and HSP90, cBioPortal database reveals a positive correlation between STK32C and HSP90 at mRNA level in colorectal cancer (P < 0.01, r = 0.12)." (PMID 41208890, 2025).
COVID-19 (1 paper, 2022). A disease caused by infection with severe acute respiratory syndrome coronavirus 2. "Another two genes, KNDC1 and STK32C, adjacent genes for the same SNP rs148148613, tend to be expressed higher in most of GTEx tissues of females than males, and they are stimulated in blood of COVID-19 patients." (PMID 36353114, 2022).
mastitis (1 paper, 2024). Inflammation of breast tissue during lactation or postpartum due to an obstructed duct or infection. "The same region partially overlaps the CNVR_1549_P (the region comprising the JAKMIP3, DPYSL4, STK32C, LRRC27, PWWP2B) resulted associated with clinical mastitis in Mexican Holstein Cattle." (PMID 38771855, 2024).
melanoma (1 paper, 2022). A malignant, usually aggressive tumor composed of atypical, neoplastic melanocytes. "From other validated targets in this study that have not yet been investigated in melanoma, we would like to point out MRAS, IL1R2, RAB34, LAPTM5, RDH10, and STK32C." (PMID 36139698, 2022).
pheochromocytoma (1 paper, 2025). "Consistently, tissue array reveals highly expression of STK32C in tubular adenocarcinoma and pheochromocytoma of CRCs compared to normal tissues." (PMID 41208890, 2025).
pneumococcal meningitis (1 paper, 2020). An acute purulent infection of the meninges and subarachnoid space caused by Streptococcus pneumoniae, most prevalent in children and adults over the age of 60. "Host variation in Coiled-Coil Domain Containing 33 (CCDC33) and serine/threonine kinase 32C (STK32C) were associated with susceptibility to pneumococcal meningitis." (PMID 32042572, 2020).
tumor (4 papers, 2018 to 2025). "Consistently, tumor volume and weights were significantly suppressed in STK32C depletion group compared to sham control group." (PMID 41208890, 2025). "Although the expression levels varied across individual samples, both cohorts displayed a trend of higher STK32C expression in tumor tissues compared with normal controls." (PMID 41208890, 2025). "In conclusion, our study was the precedent experiment which systematically researched the roles of STK32C in tumor progression of BC." (PMID 30022623, 2018). "Our findings suggest that the tumor-promoting effects of STK32C and STK40 in TNBC may be achieved through the regulation of YAP/TAZ." (PMID 40869130, 2025). "Additionally, tumor stages were in parallel with upregulation of STK32C." (PMID 41208890, 2025). "Here STK32C was significantly (p<0.001) overexpressed at mRNA level in CRC tissues (BRCA; tumor n = 287, normal n = 41)." (PMID 41208890, 2025). "Also, STK32C depletion reduced the growth of HCT116 cells in BALB/c nude mice compared to untreated control, which was confirmed in tumor tissues by Western blotting." (PMID 41208890, 2025).
inflammation (1 paper, 2016). Aberrant reaction of the microcirculation characterized by movement of fluid and leukocytes from the blood into extravascular tissues. "However, data mining of STK32C gene expression changes in Geoprofile datasets GSE26456 or GSE23014 revealed interesting correlations with CD4+ Treg-cell function and lung inflammation." (PMID 26999364, 2016).
STK32C also shares sentences with these, for which no sentence is quoted: Alzheimer disease (2 papers); cancer (2); colon cancer (1); triple-negative breast carcinoma (1); tubular adenocarcinoma (1).